MAP4K5 (mitogen-activated protein kinase kinase kinase kinase 5)
Description:
May play a role in the response to environmental stress. Appears to act upstream of the JUN N-terminal pathway.
Synonyms: KHS; KHS1; GCKR; MAPKKKK5
Tractability: Small molecule: a high-quality ligand is known; it belongs to a druggable protein family. Antibody: its Gene Ontology location is reachable by antibodies, with high confidence. PROTAC: it is named in the literature on targeted protein degradation; ubiquitination databases record sites on it; its protein half-life has been measured; a small molecule that binds it is known.
Target class: Protein Kinase; STE protein kinase STE20 family; STE protein kinase group; Enzyme; Kinase; STE protein kinase KHS subfamily
Gene: Protein-coding gene on chromosome 14 (50,417,845 to 50,561,126, reverse strand). Ensembl gene ENSG00000012983.
Subcellular location: Cytoplasm
Subcellular location (Human Protein Atlas): Cytosol; Plasma membrane; Primary cilium
Gene Ontology:
Molecular function: ATP binding; protein binding; protein serine kinase activity; protein serine/threonine kinase activity; MAP kinase kinase kinase kinase activity; protein kinase activity
Biological process: intracellular signal transduction; MAPK cascade
Cellular component: cytoplasm; cytosol
Genetic constraint (gnomAD): Loss-of-function variants: 17 observed, 33.38 expected, observed/expected ratio (o/e) 0.51, 90% interval 0.35 to 0.76. The upper end of that interval is the gene's LOEUF score, 0.76, which puts it in group 3 of 6, group 1 being the genes least tolerant of losing a copy. Missense variants: 340 observed, 375.53 expected, observed/expected ratio (o/e) 0.91, 90% interval 0.83 to 0.99. Synonymous variants: 141 observed, 129.47 expected, observed/expected ratio (o/e) 1.09, 90% interval 0.95 to 1.25.
Homologues: Orthologues: chimpanzee MAP4K5 (99% identical), macaque MAP4K5 (99% identical), dog MAP4K5 (98% identical), pig MAP4K5 (98% identical), rat Map4k5 (97% identical), mouse Map4k5 (96% identical), rabbit MAP4K5 (94% identical), guinea pig MAP4K5 (92% identical), tropical clawed frog map4k5 (82% identical), zebrafish map4k5 (78% identical). Paralogues in human: MAP4K3 (69% identical), MAP4K2 (51% identical), MAP4K1 (45% identical), TNIK (27% identical), MAP4K4 (27% identical), MINK1 (27% identical), SLK (23% identical), STK10 (23% identical), NRK (22% identical), TAOK1 (21% identical), TAOK3 (20% identical), TAOK2 (19% identical), and 23 more.
Diseases named in the same sentence as MAP4K5 in open-access papers:
MAP4K5 is named in the same sentence as 16 diseases in open-access papers, as found by Europe PMC text mining. Sharing a sentence is not in itself a finding about the gene and the disease. The quoted sentences say what the papers report.
pancreatic cancer (3 papers, 2016 to 2025). "Thus, expression of MAP4K5 is decreased or lost in the majority of pancreatic cancers, and low MAP4K5 levels in this malignancy are associated with epithelial-mesenchyme transition and poor prognosis." (PMID 30655532, 2019). "In addition, we observed the same correlation between the loss of MAP4K5 expression and the loss of E-cadherin expression both at the protein and mRNA levels in multiple pancreatic cancer cell lines." (PMID 27023625, 2016). "Similarly, loss of MAP4K5 protein expression was observed in majority of human pancreatic cancer cell lines compared to HPDE cells, immortalized normal pancreatic ductal cells." (PMID 27023625, 2016). "Our data suggested, for the first time, that loss of MAP4K5 expression might play a role in the progression of pancreatic cancer." (PMID 27023625, 2016). "However, the molecular mechanisms leading to the loss of MAP4K5 expression in pancreatic cancer need further investigation." (PMID 27023625, 2016). "Similar correlations between the expression of MAP4K5 and E-cadherin were observed both at protein and mRNA levels in multiple pancreatic cancer cell lines." (PMID 27023625, 2016). "Compared to these cells, all other pancreatic cancer cell lines that had low MAP4K5 expression had decreased expression of E-cadherin." (PMID 27023625, 2016). "Immunoblotting and RNA sequencing analysis were used to examine the expression of MAP4K5 and E-cadherin in pancreatic cancer cell lines." (PMID 27023625, 2016). "Our data provides a link between the loss of MAP4K5 and EMT in pancreatic cancer and may suggest that MAP4K5 signaling represents a potential therapeutic target for pancreatic cancer." (PMID 27023625, 2016). "Our results may suggest that loss of MAP4K5 expression plays a role in EMT, chemotherapy resistance and progression of pancreatic cancer." (PMID 27023625, 2016). "Furthermore, knockdown MAP4K5 in pancreatic cancer cell lines led to decreased CDH1 mRNA expression." (PMID 27023625, 2016). "Targeting impaired MAP4K5 signaling may represent a new therapeutic strategy for pancreatic cancer." (PMID 27023625, 2016). "The strong associations between the loss of MAP4K5 expression and loss of E-cadherin or reduced CES2 expression may suggest an important role of MAP4K5 in epithelial-to-mesenchymal transition, chemotherapy resistance and tumor progression in pancreatic cancer." (PMID 27023625, 2016). "Thus, targeting impaired MAP4K5 signaling may represent a new therapeutic strategy for pancreatic cancer treatment." (PMID 27023625, 2016). "Thus targeting impaired MAP4K5 signaling pathways may help to overcome the drug resistance of pancreatic cancer." (PMID 27023625, 2016). "The strong associations between low MAP4K5 expression and loss of E-cadherin, reduced CES2 expression and decreased overall survival may suggest an important role of MAP4K5 in epithelial-to-mesenchymal transition, chemotherapy resistance and tumor progression in pancreatic cancer." (PMID 27023625, 2016). "The knockdown of MAP4K5 in pancreatic cancer cell lines leads to decreased CDH1 mRNA expression, highlighting the essential role of MAP4K5 in regulating E-cadherin expression and EMT59." (PMID 41034525, 2025). "In light of previous findings that MAP4K5 is involved in the regulation of both the canonical and non-canonical Wnt signaling, we examined the functions and correlations between MAP4K5 and EMT in pancreatic cancer." (PMID 27023625, 2016). "Consistent with our immunohistochemical staining results, high level of MAP4K5 protein expression was detected in HPDE cells, immortalized normal pancreatic ductal cells, but only in 2 of 7 (28.6%) human pancreatic cancer cell lines by immunoblotting analysis." (PMID 27023625, 2016). "Therefore MAP4K5 may play an important role in regulating the expression of E-cadherin and EMT in pancreatic cancer." (PMID 27023625, 2016).
acute myeloid leukemia (1 paper, 2025). Acute myeloid leukemia (AML) is a group of neoplasms arising from precursor cells committed to the myeloid cell-line differentiation. "We extended this analysis to another tumor cell line (the human acute myeloid leukemia cell line MOLM13) that is growth resistant with the SHP2 inhibitor SHP099 after KO of the INPPL1 or MAP4K5 genes (GSE218491, GSE21223)." (PMID 40131370, 2025).
autoimmune disease (1 paper, 2025). A disorder resulting from loss of function or tissue destruction of an organ or multiple organs, arising from humoral or cellular immune responses of the individual to their own tissue constituents. "STX8 and YES1 are implicated in T-cell activation, MAP4K5, RRM2B, FOXO1, ERBB2IP and INPPL1 can promote inflammation and KIM1, MVK and BANK1 have been associated with autoimmune diseases." (PMID 40247373, 2025).
neuroblastoma (1 paper, 2021). Neuroblastoma (NB) is the most common solid, extracranial childhood tumor. "CDK11B has been shown to be involved in neuroblastoma while MAP4K5 has been suggested to have a role in stress response." (PMID 33845866, 2021).
pancreatic ductal adenocarcinoma (1 paper, 2016). An infiltrating adenocarcinoma that arises from the epithelial cells of the pancreas. "Loss of MAP4K5 expression is present in majority of pancreatic ductal adenocarcinomas and is an independent poor prognostic factor for patients with stage II PDAC." (PMID 27023625, 2016). "The major objectives of this study are to examine the expression, functions and clinical significance of MAP4K5 in pancreatic ductal adenocarcinoma (PDAC)." (PMID 27023625, 2016). "Expression of MAP4K5 in pancreatic ductal adenocarcinoma and benign pancreas samples." (PMID 27023625, 2016).
tumor (10 papers, 2015 to 2026). "Correspondingly, tumor-associated target genes including ALDH3A2, SEMA3F, MAP4K5, and TRIP13 were upregulated, whereas PIK3IP1, AGO2, MMP2, and RALBP1 were suppressed." (PMID 41897301, 2026). "The median survival was 21.2 ± 2.6 months in MAP4K5-low group compared to 40.6 ± 6.2 months in patients whose tumor was MAP4K5-high (P = 0.02, log-rank test)." (PMID 27023625, 2016). "In contrast, there is conservation of MAP3K1 and MAP4K5, which may promote pro-tumor inflammatory response." (PMID 38704802, 2024). "In addition, our data identifying MAP4K5 as a suppressor of Src-induced transformation support an emerging role for this kinase as a negative regulator of tumor progression." (PMID 30655532, 2019). "Sequencing identified germline and tumor amplified, expressed, high-impact druggable variants in two genes (ABL1, NOTCH1) and expressed, medium impact variants in three additional genes (MDM4, PAK4, MAP4K5)." (PMID 31208434, 2019). "Interestingly, we identified two neoantigen candidates in two patients (ImmuNEO-4 and −23) that were derived from shared variants in MAP4K5 (IN_04_F, 1.5% FDR; shared between 32 tumor samples) and in AC024075.2 (IN_23_A, 4.3% FDR, shared between 24 tumor samples), respectively." (PMID 37532709, 2023). "Cancer cells in both KRAS-mut and NEK groups conserved members of the MEK family while WT tumor also conserved MAP4K5, which does not have a known role in LUAD." (PMID 36612014, 2022).
cancer (4 papers, 2012 to 2022). A tumor composed of atypical neoplastic, often pleomorphic cells that invade other tissues. "In PDAC cases that were MAP4K5 positive, diffuse cytoplasmic staining were observed only carcinoma cells." (PMID 27023625, 2016). "In addition to cancer, TAOK1 and MAP4K5 is implicated in neurodegenerative disorders." (PMID 33167727, 2021).
MAP4K5 also shares sentences with these, for which no sentence is quoted: cardiac hypertrophy (1 paper); colorectal cancer (1); diabetes (1); dyslipidemia (1); intellectual disabilities (1); lung carcinoma (1); melanoma (1); neurological disorders (1); osteonecrosis (1).